USP24 (ubiquitin specific peptidase 24)
Description:
Plays a positive role on ferritinophagy where ferritin is degraded in lysosomes and releases free iron.
Synonyms: KIAA1057
Tractability: PROTAC: ubiquitination databases record sites on it; its protein half-life has been measured; a small molecule that binds it is known.
Target class: Enzyme; Hydrolase
Gene: Protein-coding gene on chromosome 1 (55,066,359 to 55,215,753, reverse strand). Ensembl gene ENSG00000162402.
Subcellular location (Human Protein Atlas): Nucleoplasm; Cytosol
Pathways (Reactome):
Metabolism of proteins: Ub-specific processing proteases
Gene Ontology:
Molecular function: protein binding; cysteine-type deubiquitinase activity
Biological process: protein deubiquitination
Cellular component: cytosol; nucleoplasm
Genetic constraint (gnomAD): Loss-of-function variants: 86 observed, 285.38 expected, observed/expected ratio (o/e) 0.3, 90% interval 0.25 to 0.36. The upper end of that interval is the gene's LOEUF score, 0.36, which puts it in group 1 of 6, group 1 being the genes least tolerant of losing a copy. Missense variants: 2,223 observed, 2,824.9 expected, observed/expected ratio (o/e) 0.79, 90% interval 0.76 to 0.81. Synonymous variants: 1,058 observed, 1,010.3 expected, observed/expected ratio (o/e) 1.05, 90% interval 1 to 1.1.
Homologues: Orthologues: chimpanzee USP24 (99% identical), macaque USP24 (99% identical), dog USP24 (99% identical), pig USP24 (99% identical), rabbit USP24 (98% identical), mouse Usp24 (98% identical), rat Usp24 (98% identical), guinea pig USP24 (90% identical), tropical clawed frog usp24 (87% identical). Paralogues in human: USP9X (12% identical), USP9Y (11% identical), USP31 (9% identical), USP32 (9% identical), USP34 (8% identical), USP36 (8% identical), USP43 (8% identical), USP15 (8% identical), USP4 (7% identical), USP42 (7% identical), USP19 (7% identical), USP6 (7% identical), and 59 more.
Diseases named in the same sentence as USP24 in open-access papers:
USP24 is named in the same sentence as 56 diseases in open-access papers, as found by Europe PMC text mining. Sharing a sentence is not in itself a finding about the gene and the disease. The quoted sentences say what the papers report.
lung carcinoma (18 papers, 2017 to 2025). "In our previous study, we demonstrated that USP24 expression was upregulated in most late-stage lung cancer patients due to increased mRNA stability caused by single nucleotide polymorphisms (SNPs) or RNA editing." (PMID 38491202, 2024). "Our previous studies have shown that USP24 is overexpressed in lung cancer and in the tumor‐associated microenvironment (TAM) and is involved in tumor malignancy and drug resistance." (PMID 38140768, 2024). "In our previous study, we demonstrated that USP24 expression was upregulated in most late-stage lung cancer patients due to increasing mRNA stability caused by SNPs or RNA editing." (PMID 33846536, 2021). "Our previous studies indicated that USP24 is upregulated in cancer cells and that tumor-associated macrophages to promote lung cancer malignancy." (PMID 33846536, 2021). "Our previous studies also indicated that USP24 upregulation in lung cancer cells and the tumor-associated macrophages enhanced cancer malignancy through increases in IL6 expression and secretion via p300-mediated acetylation of histone H316." (PMID 33257797, 2020). "Our recent study found that USP24 is increased in M2 tumor-associated macrophages (TAMs), thereby promoting lung cancer malignancy through an increase in IL6 expression." (PMID 31133011, 2019). "In our previous study, we demonstrated that USP24 expression was upregulated in most late-stage lung cancer patients due to increased mRNA stability caused by SNPs or RNA editing." (PMID 30266897, 2018). "Although early-stage lung cancer patients with EGFR mutations exhibit a higher correlation with lower USP24 expression, other patients (especially at the late stage) express higher levels of USP24." (PMID 27991932, 2017). "Here we found an inverse correlation between the USP24 level and EGFR mutations in lung cancer clinical samples, suggesting that USP24 might negatively regulate cancer formation." (PMID 27991932, 2017). "Furthermore, we examined whether infiltration of USP24+PD-1+CD8+ T cells was associated with cancer progression in lung cancer." (PMID 40238877, 2025). "On the other hand, USP24 stabilizes p300, increasing histone H3 acetylation at the IL-6 promoter, which enhances IL-6 expression in M2 macrophages and promotes lung cancer progression." (PMID 40375990, 2025). "Recently, we used a structure modelling method to screen a novel specific USP24 inhibitor, USP24-i-101, which can inhibit drug resistance during lung cancer therapy in autophagy activation dependent manner." (PMID 40448065, 2025). "Based on these findings, the upregulation of USP24 in cancer cells plays a critical role in promoting lung cancer metastasis." (PMID 40448065, 2025). "Clinically, patients with lung cancer exhibiting high USP24 expression in tumor-infiltrating CD8+ T cells display exhausted features and show unfavorable responses to immunotherapy." (PMID 40238877, 2025). "Previous studies have reported that USP24 inhibition suppresses the migration of lung cancer cells, while USP24 silencing promotes cell proliferation and migration in hepatocellular carcinoma." (PMID 40715045, 2025). "For instance, USP24 controls PD-L1 stability in lung cancer cells, suggesting its role in repressing T cell activity in USP24 highly expressed cancers." (PMID 40238877, 2025). "Our previous study also revealed that p300 is one of the substrate of USP24 to regulate NF-κB expression in lung cancer cells." (PMID 40448065, 2025). "In this study, we found that targeting USP24 by USP24-i-101 can overcome Taxol- or gefitinib-induced drug resistance in lung cancer." (PMID 38491202, 2024). "In this study, we found that targeting USP24 by the specific USP24 inhibitors, USP24-i and its analogues, dramatically activated autophagy in the interphase and mitotic periods of lung cancer cells by inhibiting E2F4 and TRAF6, respectively." (PMID 38491202, 2024).
lung carcinoma (continued). "Next, we used USP24-i-101 to study the effect of targeting USP24 on drug-resistant EGFRL858R mice with lung cancer induced by gefitinib treatment for a long time (217 days)." (PMID 38491202, 2024). "The levels of USP24 and PD-L1 in lung tumors of lung cancer patients indicated that a partially positive correlation between USP24 and PD-L1." (PMID 38491202, 2024). "Here, we used EGFRL858R*USP24WT and EGFRL858R*USP24C1695A mice to study the role of USP24 in the drug resistance of lung cancer acquired by gefitinib treatment." (PMID 38491202, 2024). "In our previous studies, we developed small‐molecule inhibitors targeting ubiquitin‐specific peptidase 24 (USP24) to combat drug‐resistant lung cancer." (PMID 38140768, 2024). "Genomic instability and PD-L1 levels were increased in drug resistant lung cancer cells and were inhibited by USP24-i-101 treatment or knockdown of USP24." (PMID 38491202, 2024). "Next, the effect of targeting USP24-induced autophagy on chemotherapy- and targeted therapy-induced drug-resistant lung cancer cells was studied." (PMID 38491202, 2024). "Our recent results also indicated that USP24 is downregulated in the early stage of lung cancer, which is advantageous for tumorigenesis." (PMID 33257797, 2020). "The levels of USP24 and its substrates in the initiation of lung cancer were determined in KrasG12D-induced lung cancer mice." (PMID 33257797, 2020). "USP24 knockdown (KD) in H1299 lung cancer cells and U2OS bone cancer cells decreased levels of the BRD-containing proteins including BRG1, BRD7, BRD1, BRD3, GCN5, PCAF, and TIF1α." (PMID 33257797, 2020). "Herein we found that USP24-mediated stabilization of BRD-containing proteins inhibited lung cancer cell growth but also increased the migratory ability of lung cancer cells, which is consistent with the effect of USP24 on lung cancer progression." (PMID 33257797, 2020). "Our previous studies indicated that USP24 is downregulated in patients with early stage lung cancer." (PMID 31133011, 2019). "A previous study reported that USP24 can stabilize MDM2 then decrease the Suv39h1 level resulting in lung cancer metastasis." (PMID 30911287, 2019). "In this study, another interesting point is the discovery of distinct molecular mechanisms regulating IL-6 expression in M2 macrophages and lung cancer cells in response to USP24." (PMID 30266897, 2018). "In this study, we studied the effect of USP24 in lung cancer malignancy through the USP24/p300/ NF-κB/IL-6 regulatory axis." (PMID 30266897, 2018). "Taken together, these data showed that upregulated USP24 in M2 macrophages positively regulates lung cancer malignancy." (PMID 30266897, 2018). "Based on these findings, we concluded that upregulated USP24 in cancer cells plays a critical role promoting lung cancer metastasis." (PMID 30266897, 2018). "The cDNA microarray data revealed that many NF-κB target genes were also downregulated in USP24-knockdown lung cancer cells, and several of the genes were also found to be related to metastasis." (PMID 30266897, 2018). "USP24 knockdown decreased, while USP24 overexpression increased, the transwell chemotactic, and migratory properties of lung cancer cells." (PMID 30266897, 2018). "The detailed mechanisms regarding how USP24 regulates IL-6 expression in M2 macrophages and lung cancer cells require further clarification." (PMID 30266897, 2018). "Because p300 was decreased in USP24-knockdown lung cancer cells, the histone H3 acetylation level in the IL-6 promoter was also examined after USP24 knockdown in A549 cells." (PMID 30266897, 2018).
lung carcinoma (continued). "The results showed that silencing USP24 in lung cancer cells decreased histone 3 acetylation at the IL-6 promoter region, implying that the transcriptional activity of IL-6 is inhibited by USP24 knockdown." (PMID 30266897, 2018). "In this study, USP24 expression was increased not only in lung cancer cells but also in M2 macrophages." (PMID 30266897, 2018). "Our previous study also showed that USP24 was increased in lung cancer cell lines with higher metastasis activity." (PMID 30266897, 2018). "These TILs expressed higher USP24 levels than the surrounding cancer cells in seven lung cancer patient specimens positive for USP24 expression." (PMID 30266897, 2018). "Because IL-6 in the tumor-associated microenvironment is not only expressed by M2 macrophages but also by cancer cells themselves, we assessed IL-6 levels in lung cancer cells after USP24 knockdown." (PMID 30266897, 2018). "We previously showed that USP24 is highly expressed in late-stage lung cancer patients and promotes cancer cell metastasis by regulating metastasis-related gene expression." (PMID 30266897, 2018). "Next, we collected 50 human lung cancer specimens to study the correlation among USP24, p300, β-TrCP and DNMT1 in human lung cancer." (PMID 30266897, 2018). "After validating the specificity of anti-USP24 antibodies, USP24 levels were studied in human lung cancer samples using immunohistochemistry (IHC)." (PMID 30266897, 2018). "Conditioned medium from USP24-knockdown M2 macrophages decreases the migratory and chemotactic activity of lung cancer cells and the angiogenic properties of human microvascular endothelial cell 1 (HMEC-1)." (PMID 30266897, 2018). "IL-6 expression is significantly decreased in USP24-knockdown M2 macrophages and lung cancer cells, and IL-6-replenished conditioned medium restores the migratory, chemotactic and angiogenetic properties of the cells." (PMID 30266897, 2018). "We collected lung cancer samples from a doxycycline-induced lung cancer mouse model to study the correlation among USP24, p300 and NF-κB in M2 macrophages in vivo." (PMID 30266897, 2018). "There are different regulatory mechanisms controlling USP24-induced IL-6 expression in M2 macrophages and lung cancer cells." (PMID 30266897, 2018). "To study the role of USP24 during tumorigenesis, we assessed USP24 levels in two doxycycline-induced lung cancer transgenic mouse models (KrasG12D and EGFRL858R)." (PMID 27991932, 2017). "Our data support that, together with other oncogenes such as Kras or EGFR, USP24 downregulation positively affected the efficacy of lung cancer formation." (PMID 27991932, 2017). "We investigated the relevance between the USP24 level and the EGFR mutation in clinical lung cancer specimens and found that patients with the EGFR mutation were more highly correlated with reduced USP24 expression." (PMID 27991932, 2017). "Notably, late-stage lung cancer specimens were highly infiltrated with USP24+PD-1+Lag-3+CD8+ dysfunctional T cells, while USP24 and Tex markers were barely expressed in patients with early-stage lung cancer." (PMID 40238877, 2025). "To investigate the clinical significance of USP24-promoted PD-1 expression, we performed multiplex IF-immunohistochemistry (IF-IHC) staining in surgically resected tumor specimens of 90 patients with lung cancer." (PMID 40238877, 2025). "In lung cancer, IL-6/STAT3-inducible USP24 stabilizes PD-1 protein by deubiquitinating K48-linked ubiquitin chains; USP24 inhibition suppresses T-cell exhaustion and restores immunotherapy responsiveness, implicating IP-regulated deubiquitination in immune escape." (PMID 41293269, 2025). "In addition, we developed a specific USP24 inhibitor to overcome drug resistance acquired during chemotherapy or targeted therapy in lung cancer." (PMID 40238877, 2025).
lung carcinoma (continued). "In addition, USP24 expression in PBMCs or tumor specimens from patients with lung cancer serves as a potential biomarker to facilitate the selection of R patients before receiving ICB therapy." (PMID 40238877, 2025). "Furthermore, a volcano plot of DEGs in Taxol‐resistant A549 lung cancer cells treated with the USP24 inhibitor showed that cholesterol and fatty acid biosynthesis enzymes were upregulated, and they are presented in red." (PMID 38140768, 2024). "However, many cases with higher USP24 expression still have low PD-L1 expression, indicating that other unknow factor(s) are also essential for the regulation of PD-L1 during lung cancer progression." (PMID 38491202, 2024). "Our previous studies indicated that USP24 in macrophages can regulate the tumor microenvironment to enhance lung cancer progression, indicating that USP24 might also be critical for the regulation of T-cell development and differentiation." (PMID 38491202, 2024). "It has been reported that USP24 is overexpressed in the late stage of lung cancer." (PMID 34326684, 2021). "Our previous studies indicated that USP24 positively regulates lung cancer metastasis." (PMID 33257797, 2020). "Therefore, the DUB USP24 is tightly regulated during lung cancer progression and affects cancer growth and malignancy through stabilizing its substrates by removing the ubiquitin." (PMID 33257797, 2020). "Interestingly, we found that USP24 stabilizes p300 to manipulate the acetylation level of histone 3 in the IL-6 promoter region in M2 macrophages and lung cancer cells." (PMID 30266897, 2018). "Here, we also observed that USP24 in lung cancer cells increased IL-6 expression." (PMID 30266897, 2018). "Here, we found that USP24 expression is upregulated in M2 macrophages and lung cancer cells." (PMID 30266897, 2018). "Adding the physiological dose of IL-6 to the media of USP24-knockdown cells can rescue the effect of USP24 knockdown, suggesting that the USP24-mediated IL-6 in M2 macrophages and in lung cancer is an important factor that affects USP24-induced lung cancer malignancy." (PMID 30266897, 2018). "In lung cancer cells, the IL-6 promoter activity was decreased after USP24 knockdown." (PMID 30266897, 2018). "Therefore, the methylation marks in control and USP24-knockdown M2 macrophages and A549 lung cancer cells were investigated." (PMID 30266897, 2018). "Finally, CL1–5 lung cancer cells pretreated with USP24-knockdown conditioned medium were injected into SCID mice through the tail vein to examine metastatic ability." (PMID 30266897, 2018). "In addition, we found that USP24 stabilized p300 in M2 macrophages and lung cancer cells to regulate cancer progression." (PMID 30266897, 2018). "Taken together, these data revealed that KrasG12D- or EGFRL858R-mediated pathways negatively regulated USP24 expression, which might trigger lung cancer formation." (PMID 27991932, 2017). "Finally, USP24 knockdown increased the cell numbers and cell viability in A549 and lung primary cells, suggesting that USP24 negatively regulated lung cancer formation." (PMID 27991932, 2017). "Furthermore, we investigated the clinical relevance of USP24 between normal lung tissue and lung cancer specimens for immunohistochemistry staining with an antibody against USP24." (PMID 27991932, 2017). "Finally, we used samples from clinical lung cancer patients to study the relevance between USP24 and its substrates." (PMID 27991932, 2017). "In this study, several cancer-related proteins (Bax, p300, E2F4 and securin) have been proven to be substrates of ubiquitin-specific peptidase 24 (USP24), and relevance has been shown between USP24 and its substrates in samples from clinical lung cancer patients." (PMID 27991932, 2017). "USP24 in other cells might also be important for lung cancer drug resistance." (PMID 38491202, 2024).